TRIM26 (tripartite motif containing 26)
Diseases named in the same sentence as TRIM26 in open-access papers (continued):
Sharing a sentence is not in itself a finding about the gene and the disease.
tumor (27 papers, 2017 to 2026). "TRIM26 is implicated in aspects of immunity, inflammation, and tumor development." (PMID 38956921, 2024). "Specifically, USP39 promotes HCC progression by inhibiting the degradation of ZEB1 through its deubiquitylation function, whereas TRIM26 exerts tumor suppressor functions by ubiquitinating degraded ZEB1." (PMID 40990019, 2025). "On the one hand, TRIM26 was reported to play a potential tumor suppressive role in some types of human cancers." (PMID 38260302, 2024). "The western blot experiment verified an elevation in the TRIM26 protein level in the tumor tissues of the LV-TRIM26 groups." (PMID 38773612, 2024). "Our investigation revealed valuable information about the tumor suppressive function of TRIM26 in ccRCC and its ability to predict outcomes." (PMID 38773612, 2024). "The data together revealed that TRIM26 plays a function as a tumor suppressor in the carcinogenesis and development of ccRCC." (PMID 38773612, 2024). "The levels of p-Akt, p-GSK3β, β-catenin, and c-Myc were notably decreased in T24 and J82 cells with TRIM26 knockdown in bladder cancer, resulting in the suppression of tumor cell proliferation, migration, and invasion." (PMID 38956921, 2024). "Inhibition of TRIM26 phosphorylation causes a reduction in GPX4 K63-linked polyubiquitination and diminishes GPX4 protein levels in tumor cells." (PMID 37872147, 2023). "Tumor growth curve results indicated that TRIM26 overexpressed xenografts, as confirmed by western blotting and immunohistochemistry, grew significantly slower than control xenografts." (PMID 37591850, 2023). "Taken all together, these results concluded that TRIM26 promotes NSCLC tumor growth by suppressing PBX1 via the ubiquitin-proteasomal pathway." (PMID 37324936, 2023). "Downregulation of TRIM26 expression in HCC cells significantly promotes tumor growth, with a greater volume of tumors." (PMID 36707504, 2023). "The results showed that overexpression of TRIM26 markedly promoted the tumor growth while knockout of TRIM26 suppressed NSCLC tumor growth in mice." (PMID 37324936, 2023). "As a tumor suppressor, TRIM26 shows a decreasing tendency in a variety of cancers such as papillary cancer, non-small cell lung cancer, nasopharyngeal carcinoma and HCC." (PMID 36707504, 2023). "This tumor cell-specific pseudobulk expression analysis also revealed a significant correlation between TRIM26 and SOX2 expression with a trend towards correlation in a second scRNA-seq dataset." (PMID 34732716, 2021). "Deregulation of the deubiquitinase USP39 and the E3 ubiquitin ligase TRIM26 plays an essential role in tumor progression." (PMID 33649471, 2021). "BLI over a period of 20 weeks demonstrated diminished tumor growth in animals bearing TRIM26 knockdown GSCs, particularly in the first 16 weeks." (PMID 34732716, 2021). "To verify that TRIM26 is expressed in GBM tumor cells, we subjected freshly dissociated tumor samples from three patients to single-cell RNA-sequencing (scRNA-seq)." (PMID 34732716, 2021). "The results showed that USP39 knockdown led to an obvious reduction in tumor metastasis, while TRIM26 downregulation enhanced the tumor metastasis and reversed the reduction of shUSP39-related cell metastasis and the number of nodules in the lung." (PMID 33649471, 2021). "In detail, USP39 inhibits ZEB1 degradation through its deubiquitination function to promote HCC progression and TRIM26 degrades ZEB1 via ubiquitination to exert tumor-suppressive functions." (PMID 33649471, 2021). "Strikingly, there were few tumor cells observed in mice injected with TRIM26 knockdown GSCs, precluding any robust quantitative analysis of SOX2 immunofluorescence in these brains." (PMID 34732716, 2021). "Interrogation of the TCGA database confirmed that TRIM26 is highly expressed in GBM tumor specimens relative to normal brain." (PMID 34732716, 2021). "TRIM26 may regulate tumor progression via the Wnt/β-catenin pathway and is linked to immune infiltration." (PMID 42040893, 2026).
tumor (continued). "Furthermore, analysis of protein expression in tumor tissues revealed that evodiamine consistently inhibited the expression of TRIM26 and GPX4 proteins, aligning with the in vitro findings." (PMID 40420092, 2025). "Xenograft experiments further validated the tumor-promoting role of TRIM26 in CRC." (PMID 38260302, 2024). "Finally, we have discussed our outlook and future research directions of TRIM26 with the aim of providing new ideas for the development of novel antiviral drugs and enriching tumor therapeutic modalities." (PMID 38956921, 2024). "Therefore, it is of great interest to develop therapeutic approaches for ccRCC patients by restoring TRIM26 expression in tumor cells." (PMID 38773612, 2024). "Moreover, elevated cellular MDA, 4-HNE and ROS levels were observed in TRIM26-knockdown tumor cells, which was reversed by the re-expression of GPX4." (PMID 37872147, 2023). "TRIM26 interacts with PBX1 and mediates its K48-linked polyubiquitination and proteasomal degradation therefore inhibiting PBX1 transcriptional activity and promotes NSCLC cell proliferation and tumor survival." (PMID 37324936, 2023). "Moreover, the IB analyses on tumor tissues from xenografts showed that overexpression of TRIM26 decreased PBX1 and RNF6, while knockout of TRIM26 led to upregulation of PBX1 and RNF6." (PMID 37324936, 2023). "TRIM26 has an E3 ubiquitin ligase activity, which is involved in the degradation of numerous target proteins and may act as a novel tumor suppressor of HCC." (PMID 33649471, 2021). "TRIM26 was detectable in malignant cells from all three tumor samples." (PMID 34732716, 2021). "Finally, we asked if the TRIM26/WWP2 ubiquitin signaling pathway is relevant for in vivo GBM tumor formation in GSC-based mouse models." (PMID 34732716, 2021). "However, a potential tumor suppressor role for TRIM26 and the mechanism involved require further investigation." (PMID 29610152, 2018). "Finally, we tested whether TRIM26 can exert similar tumor-inhibitory activity in vivo by using a xenografts mouse model." (PMID 37591850, 2023). "TRIM26 depletion attenuated E2F3 induced NF-κB activation and tumor growth, whereas its restoration rescued these effects." (PMID 42088415, 2026). "The E3 ubiquitin ligase activity of TRIM26 targeting ZEB1 and to act as a tumor suppressor in HCC was studied before." (PMID 38260302, 2024). "This study uncovered that the E3 ubiquitin ligase activity of TRIM26 was previously shown to target ZEB1, an oncoprotein crucial for the development of HCC and thus to act as a tumor suppressor in HCC." (PMID 38260302, 2024). "TRIM26, PTPN6 (a cytoplasmic phosphatase), and BEX1 play critical roles in tumor immune inflammation." (PMID 38814177, 2024). "TRIM26 functions as an E3 ligase to facilitate the ubiquitination and degradation of PBX1 in the proteasome, thereby promoting tumor growth." (PMID 38956921, 2024). "In addition to its involvement in oncogenesis, TRIM26 may also function as a tumor suppressor." (PMID 38773612, 2024).
tumor (continued). "In conclusion, TRIM26 is a ubiquitin ligase of PBX1 and it promotes while PBX1 inhibits NSCLC tumor growth." (PMID 37324936, 2023). "Next, we analyzed the expression profiles of TRIM26 in NSCLC patients and its biological activity in vivo on NSCLC tumor growth." (PMID 37324936, 2023). "In the present study, we added that TRIM26 also promotes NSCLC and it clearly demonstrated that TRIM26 is highly expressed in NSCLC cells and promotes NSCLC cell proliferation, migration and tumor growth." (PMID 37324936, 2023). "In summary, the present study demonstrates TRIM26 is a first reported ubiquitin ligase of PBX1 and elucidates the detailed mechanism under TRIM26 promotes NSCLC cell proliferation and tumor growth by targeting PBX1." (PMID 37324936, 2023). "Our previous study also showed that TRIM26 suppresses HCC by ubiquitinating ZEB1, a crucial driver of tumor by inducing the EMT in tumor epithelial cells." (PMID 36707504, 2023). "In vivo, knockdown of TRIM26 inhibited, while GPX4 re-expression restored, GBM intracranial tumor growth, which in turn altered the overall survival of tumor-bearing mice." (PMID 37872147, 2023). "Accumulating evidence suggests that TRIM26, a member of the TRIM family proteins, functions as a pro-oncogenic or tumor-suppressor protein in different cancer types." (PMID 37872147, 2023). "Previous studies have elucidated that TRIM21, TRIM26, TRIM35, TRIM50, and TRIM56 acted as tumor suppressors by inhibiting tumor cell proliferation, and TRIM3, TRIM16, TRIM21, TRIM25, and TRIM26 negatively regulated migration and invasion in HCC cells." (PMID 35142083, 2022). "Among these, TRIM24, TRIM26 were identified as tumor suppressors in the development of HCC, whereas TRIM31 was identified as a tumor promoter for HCC5,15,19." (PMID 29789583, 2018). "TRIM3, TRIM16 and TRIM26 down-regulation contributes to poor prognosis in patients with HCC, suggesting the tumor suppressor function in HCC." (PMID 29898761, 2018). "Next, we tested if TRIM26 and WWP2 control SOX2 protein levels in tumor cells in vivo." (PMID 34732716, 2021). "To provide further validation for TRIM26 expression in malignant cells, we used an independent, published scRNA-seq dataset of 28 GBM tumors, which demonstrated that TRIM26 is more highly expressed in GBM tumor cells compared to nonmalignant cells." (PMID 34732716, 2021). "Furthermore, TRIM26 silencing could significantly reverse the reduction of USP39 knockdown cell proliferation, in tumor size and weight." (PMID 33649471, 2021).
cancer (20 papers, 2017 to 2025). A tumor composed of atypical neoplastic, often pleomorphic cells that invade other tissues. "Unlike USP39, which hinders the degradation of ZEB1 by deubiquitination, TRIM26 carries out its cancer-causing role by promoting the degradation of ZEB1 through ubiquitination." (PMID 38956921, 2024). "TRIM26’s functions in cancers and their underlying mechanisms just began to be unveiled less than a decade ago." (PMID 38260302, 2024). "Dysregulation of TRIM family proteins, particularly TRIM26, has been also implicated in several cancers." (PMID 33649471, 2021). "This virtually mimics a low immune response in a cancer patient with low TRIM26 expression and further supports the presence of a potential TRIM26‐associated mechanism underlying immune escape of cancer cells." (PMID 29956500, 2018). "TRIM26 is an under-studied E3 ubiquitin ligase, though it has been shown to play either anti-cancer or oncogenic role in cancer development, pending on cancer types, over the past five years." (PMID 38260302, 2024). "TRIM26 has been identified as a prototypical E3 Ub ligase and functions in a ubiquitination-dependent way in several types of cancer." (PMID 38773612, 2024). "While TRIM26’s oncogenic potential has been recognized in various cancer types, this research contributes novel insights specific to CRC." (PMID 38260302, 2024). "Tripartite motif-containing protein 26 (TRIM26) is an E3 ubiquitin ligase that exhibits divergent roles in various cancer types (oncogenic and anti-oncogenic)." (PMID 38260302, 2024). "In endometrial cancer, TRIM26 inhibits cancer growth by regulating the AKT pathway and apoptotic processes and correlates with survival indicators." (PMID 38956921, 2024). "Further mechanistic studies of the TRIM26-induced cancer-inhibiting effects revealed that TRIM26 regulates MEK/ERK signaling by promoting the degradation of RACK1." (PMID 37591850, 2023). "In vitro studies with HCC cells showed that inhibiting TRIM26 led to increased cancer cell proliferation and metastasis." (PMID 36873737, 2023). "There were a few types of research that focused on the function and mechanism of TRIM26 for patients with cancer." (PMID 35617983, 2022). "We also used the UALCAN pan-cancer view function to reveal expression patterns for TRIM26 across 24 TCGA cancer vs normal tissues." (PMID 35617983, 2022). "First, TRIM26, as a mediating gene associated with BLCA, was proved to play a key role in several types of cancers." (PMID 34464378, 2021). "Cumulatively, these data highlight the importance of TRIM26 in controlling cellular processes required for the maintenance of genome stability, and in prevention of human disease development such as cancer." (PMID 27924031, 2017). "This suggests that TRIM26 may play a regulatory role in the transduction cascade of mTOR signaling, which is commonly disrupted in human cancer." (PMID 38773612, 2024). "Looking into TRIM26’s role as anti-cancer, multiple studies support this effect." (PMID 38260302, 2024). "TRIM26 has also been extensively documented in various other types of cancers." (PMID 38956921, 2024). "Recently, more attention was paid to the functions of TRIM26 in malignant tumors." (PMID 37591850, 2023). "Current studies have indicated that TRIM26 is downregulated in several cancers." (PMID 33649471, 2021). "This suggests that the TRIM26 may be involved in cancer immune escape." (PMID 29956500, 2018). "Tripartite motif-containing 26 (TRIM26), a member of the TRIM protein family, exerts dual function in several types of cancer." (PMID 38773612, 2024). "Tripartite motif-containing 26 (TRIM26), a protein belonging to the TRIM family, has been shown to have significant involvement in several physiological and pathological processes, including ferroptosis, inflammation, antiviral immunity, and cancer." (PMID 38773612, 2024).
cancer (continued). "ZEB1 is a crucial inducer of EMT to promote the metastasis of cancer cells, but whether its stability is regulated by USP39 or TRIM26 in HCC remains enigmatic." (PMID 33649471, 2021). "In particular, six candidates (TRIM10, TRIM15, TRIM26, TRIM39-RPP21, TRIM62, and TRIM66) are members of the large tripartite motif (TRIM) family that consists of ubiquitin ligases involved in both innate immunity and cancer progression." (PMID 30102725, 2018). "TRIMs 3, 8, 13, 16, 21, 62 are downregulated in many of the main cancers worldwide (breast, gastric, liver, lung, osteosarcoma, prostate, kidney), while some TRIMs are under-expressed in a cancer-specific way (e.g., TRIM15 in gastric cancer, TRIM26 in liver, TRIM58 in lung)." (PMID 33673719, 2021). "TRIM26 may influence immune response in both NPC cells and PBMCs, but we did not know whether downregulation of TRIM26 would weaken immune response of immune or cancer cells." (PMID 29956500, 2018).
infection (15 papers, 2015 to 2026). The state of being infected such as from the introduction of a foreign agent such as serum, vaccine, antigenic substance or organism. "These include murine genes incompatible with HCV biology (CD81, OCLN, TRIM26, CypA) and those murine factors that actively inhibit infection (CD302, CR1L)." (PMID 40899815, 2025). "Given the extent to which mutations in the E1E2 glycoproteins are dispensable for Mad18 murine tropism in vitro, it is conceivable that HCV Mad18 has adapted to some combination of murine CypA or TRIM26 in order to promote infection." (PMID 40899815, 2025). "This would allow for an in-depth investigation of the interactions and mechanisms between TRIM26 and viruses throughout the natural course of infection." (PMID 39596676, 2024). "The results showed that the overexpression of TRIM26 strongly inhibited the reporter activation induced by poly (I:C) (polyinosinic-polycytidylic acid) transfection and Sendai virus (SeV) infection in a dose-dependent manner." (PMID 38965634, 2024). "We constructed ccRCC cell lines (786-O, Caki-1) with stable TRIM26 overexpression through a lentivirus infection approach." (PMID 38773612, 2024). "For example, it has been found that TRIM26 restricts the infection of EB virus in nasopharyngeal epithelial cells by connecting with HSP-90β through K48-linked ubiquitination." (PMID 38731834, 2024). "How Trim26 affects neutrophil function at different stages of infection requires further investigation." (PMID 38166150, 2024). "We found that the transcription levels of CXCL1 and CXCL2 were strongly increased in Trim26–/–mice at 1–5 days post-infection." (PMID 38166150, 2024). "Before the infection studies, we assessed the TRIM26 KD efficiency by reverse transcription—quantitative polymerase chain reaction (qPCR) and western blotting." (PMID 37604854, 2023). "Using immunofluorescent microscopy, we showed that infection with HSV-2 induces nuclear accumulation of TRIM26." (PMID 33419081, 2021). "Both WT VK2 and TRIM26 KO cell lines showed significant increase in HSV-2 GFP infection after BX-795 treatment, a result that confirms that inhibition of the IRF3 pathways contributes to increased HSV-2 infection." (PMID 33419081, 2021). "In summary, our work has unveiled a mechanism by which HSV-2 is able to hijack a host protein, TRIM26, in order to attenuate innate antiviral responses and thereby benefit its infection and replication in vaginal epithelial cells of the FRT." (PMID 33419081, 2021). "We found that HSV-2 infection upregulated TRIM26 gene expression 200-fold after 12 h of infection and 150-fold after 24 h post infection, as compared to mock controls." (PMID 33419081, 2021). "This suggests that infection with HSV-2 promotes accumulation of TRIM26 protein in the nucleus between 6 and 24 h after HSV-2 infection." (PMID 33419081, 2021). "Additionally, Trim26−/− mice exhibited significantly reduced proportions of macrophages, inflammatory monocytes in ascites, and T cells in the spleen following infection." (PMID 41652078, 2026). "Furthermore, the secretion of CXCL1 in the serum of Trim26–/–mice on day 5 post-infection was significantly higher than that in Trim26+/+ mice." (PMID 38166150, 2024). "Furthermore, we also found that COX-5B was significantly up-regulated, while TRIM25, TRIM21, TRIM27 and TRIM26 were significantly down-regulated in the PAMs with a PRRSV-ADE infection in this study." (PMID 36680075, 2022). "Furthermore, the expression of several innate immune response regulators (COX-5B, MMP-9, TRIM21, TRIM25 and TRIM26) in the PAMs were also regulated differently during the PRRSV-ADE infection." (PMID 36680075, 2022). "Moreover, it has been shown that TRIM26 interacts with IRF3 in the nucleus after infection with Sendai virus (SeV) in macrophages." (PMID 33419081, 2021).